CNN3 (calponin 3)
Description:
Thin filament-associated protein that is implicated in the regulation and modulation of smooth muscle contraction. It is capable of binding to actin, calmodulin and tropomyosin. The interaction of calponin with actin inhibits the actomyosin Mg-ATPase activity.
Tractability: PROTAC: ubiquitination databases record sites on it; its protein half-life has been measured.
Gene: Protein-coding gene on chromosome 1 (94,896,949 to 94,927,696, reverse strand). Ensembl gene ENSG00000117519.
Subcellular location (Human Protein Atlas): Actin filaments; Cytosol
Gene Ontology:
Molecular function: cadherin binding involved in cell-cell adhesion; actin filament binding; actin binding
Biological process: epithelial cell differentiation; actin filament organization; actomyosin structure organization; cell-cell adhesion
Cellular component: actin cytoskeleton; adherens junction; cytosol; focal adhesion
Genetic constraint (gnomAD): Loss-of-function variants: 10 observed, 39.42 expected, observed/expected ratio (o/e) 0.25, 90% interval 0.16 to 0.43. The synonymous counts are far from expectation, so gnomAD's model fits this gene poorly and the ratio says little. Missense variants: 266 observed, 422 expected, observed/expected ratio (o/e) 0.63, 90% interval 0.57 to 0.7. Synonymous variants: 101 observed, 145.28 expected, observed/expected ratio (o/e) 0.7, 90% interval 0.59 to 0.82.
Homologues: Orthologues: chimpanzee CNN3 (99% identical), pig CNN3 (98% identical), mouse Cnn3 (98% identical), dog CNN3 (96% identical), macaque CNN3 (95% identical), guinea pig CNN3 (94% identical), rabbit CNN3 (94% identical), rat Cnn3 (92% identical), tropical clawed frog cnn3 (85% identical), zebrafish cnn3a (83% identical), zebrafish cnn3b (81% identical), Caenorhabditis elegans cpn-2 (23% identical), and 2 more. Paralogues in human: CNN1 (62% identical), CNN2 (62% identical), TAGLN (27% identical), TAGLN3 (27% identical), TAGLN2 (27% identical).
Diseases named in the same sentence as CNN3 in open-access papers:
CNN3 is named in the same sentence as 47 diseases in open-access papers, as found by Europe PMC text mining. Sharing a sentence is not in itself a finding about the gene and the disease. The quoted sentences say what the papers report.
cervical cancer (5 papers, 2020 to 2024). A primary or metastatic malignant neoplasm involving the cervix. "Recent studies suggest that CNN3 acts as an oncogene in gastric, colorectal, and cervical cancers, and is associated with cancer cell drug resistance." (PMID 39555457, 2024). "Studies have recently shown that CNN3 functions as an oncogene in gastric, colon, and cervical cancers, and as a diagnostic marker of metastatic lymph nodes in colorectal cancer." (PMID 32667904, 2020). "CNN3 encodes a calcium regulatory protein that acts as a potential oncogene in cervical cancer." (PMID 39590360, 2024). "In xenografted cervical cancer cells, CNN3 acted as an oncogene, promoting cell viability and motility in vitro by altering the expression of ribosomal protein lateral stalk subunit P1." (PMID 34305633, 2021). "To explore the potential mechanism by which CNN3 affects the phenotypes of cervical cancer cells, we used RNA sequencing to detect changes in mRNA transcripts in SiHa cells with transfected si-NC or si-CNN3#1 (GEO Accession numbers: GSE134596)." (PMID 32051425, 2020). "In conclusion, we verified that CNN3 acts as an oncogene to promote the viability and motility of cervical cancer cells in vitro and accelerate the growth and metastasis of xenografted tumours in vivo, by affecting RPLP1 expression." (PMID 32051425, 2020). "To confirm the oncogenic effect of CNN3 on the development of cervical cancer in vivo, we constructed a cell model (SiHa) with stable knockdown of CNN3 using sh-CNN3 lentivirus." (PMID 32051425, 2020). "Further, we identified ribosomal protein lateral stalk subunit P1, also known as RPLP1, is controlled transcriptionally by CNN3, and participates in the CNN3-mediated regulation of the viability and motility of cervical cancer cells." (PMID 32051425, 2020). "To explore the mechanism by which CNN3 regulates the malignant behaviours of cervical cancer cells, we used the RNA-seq technique to identify potential downstream genes of CNN3." (PMID 32051425, 2020). "Proliferation, migration and invasion assays showed that overexpressed CNN3 promoted the viability and motility of cervical cancer cells, the opposite was observed in CNN3-knockdown cells." (PMID 32051425, 2020). "Rescue experiments further confirmed that RPLP1 restoration partially or completely reversed the proliferation, migration, and invasion inhibited by CNN3 knockdown in cervical cancer cells." (PMID 32051425, 2020). "We searched the cancer microarray database, Oncomine, and found elevated calponin 3 (CNN3) mRNA expression in cervical cancer tissues." (PMID 32051425, 2020). "By analysis of an mRNA dataset named Pyeon Multi-cancer from the Oncomine database, we found that CNN3 mRNA expression was higher in 20 cervical cancer samples than in 8 normal cervix samples." (PMID 32051425, 2020). "In conclusion, CNN3 acts as an oncogene by promoting invasion and migration in cervical cancer cells and accelerating the growth and metastasis of xenografted cervical cancer in mouse model." (PMID 32051425, 2020). "Thus, we detected CNN3 mRNA expression in 7 pairs of cervical cancer and adjacent tissues, and found higher CNN3 mRNA expression in cervical cancer tissues than in adjacent tissues, consistent with the results from the publicly availabledataset." (PMID 32051425, 2020). "Thus, our results, combined with those from previous studies, suggest that RPLP1, as a downstream gene of CNN3, plays a key role in regulating malignant behaviours of cervical cancer cells." (PMID 32051425, 2020). "Our results suggest that HPV16 oncoproteins may upregulateCNN3 expression and that CNN3 may play an oncogenic role in the development of cervical cancer." (PMID 32051425, 2020). "CNN3 affected RPLP1 mRNA expression in cervical cancer cells." (PMID 32051425, 2020). "QRT-PCR verified the increased CNN3 expression in cervical cancer compared to para-cancer tissues." (PMID 32051425, 2020).
cervical cancer (continued). "In the present study, we verified the CNN3 overexpression in cervical cancer tissues, and its role in promoting proliferation, migration, and invasion in cervical cancer cells and accelerating the growth and metastasis of xenografted tumours in immunodeficient mice." (PMID 32051425, 2020). "Our results suggest that RPLP1 plays the same role in cellular viability and activity as CNN3, and may participate in CNN3-regulated malignant behaviours in cervical cancer cells." (PMID 32051425, 2020). "Our findings provide evidence that CNN3 acts as an oncogene and may serve as a potential target for blocking the metastasis of cervical cancer." (PMID 32051425, 2020). "Our findings suggest that CNN3 may serve as a potential therapeutic target for advanced stage cervical cancer." (PMID 32051425, 2020). "In contrast, CNN3 protein expression remained unchanged when RPLP1 expression was modulated, suggesting that RPLP1 is a candidate downstream gene in cervical cancer cells." (PMID 32051425, 2020). "To explore the potential mechanism of CNN3-mediated regulation of RPLP1 expression, we examined the distribution of CNN3 in wild-type cervical cancer cells and found a trace amount of CNN3 proteins in the nucleus, which was in line with the immunofluorescence results in other studies." (PMID 32051425, 2020). "Furthermore, we observed the effect of enforcedly changing RPLP1 expression on cellular proliferation, migration, and invasion in cervical cancer cells and found that the oncogenic function of RPLP1 is similar to that of CNN3." (PMID 32051425, 2020). "Then, we detected CNN3 protein in 10 cell lines, that included non-cancer cell lines (IMR-90, 293T, 293), cervical cancer cell lines (SiHa, Hela, CaSki), ovarian cancer cell lines (A2780, SKOV3, Caov3) and an osteosarcoma cell line (U2os)." (PMID 32051425, 2020).
colorectal cancer (5 papers, 2015 to 2022). A primary or metastatic malignant neoplasm that affects the colon or rectum. "Moreover, CNN3 has been recognized as one of the more accurate and suitable diagnostic markers for metastatic lymph nodes in colorectal cancer." (PMID 32667904, 2020). "Recently, it has also been suggested that the higher CNN3 expression may play a role in increasing colorectal cancer cell invasion partially due to its association with the lower E-cadherin level." (PMID 30911294, 2019). "The relative mRNA expression of CNN3 in 14 colorectal cancer tissues was found to be lower than that in normal control tissues, and CNN3 mRNA levels are known to be significantly higher in the Dukes’ stage C group than in the control groups." (PMID 32667904, 2020). "Based on these studies, CNN3 has been known to be involved in trophoblast invasion and has been identified as a marker for lymph node metastasis in colorectal cancer." (PMID 30911294, 2019). "In colorectal cancer, the expression of CNN3 is significantly increased and is a marker for the detection of lymph node metastasis." (PMID 28159933, 2017).
osteosarcoma (5 papers, 2018 to 2025). A usually aggressive malignant bone-forming mesenchymal neoplasm, predominantly affecting adolescents and young adults. "In conclusion, high CNN3 expression was found to help in the diagnosis of osteosarcoma, and was found to be associated with poor prognosis in patients." (PMID 32667904, 2020). "In this study, we evaluated the potential diagnostic and prognostic roles of CNN3 in osteosarcoma." (PMID 32667904, 2020). "CNN3 may potentially be used as a diagnostic and prognostic biomarker for osteosarcoma and may play an oncogenic role in osteosarcoma progression." (PMID 32667904, 2020). "Also, CNN3 has been regarded as a risk factor in OS cells, that is, CNN3 may play an oncogenic role during the progression of osteosarcoma by activating the ERK1/2 and p38 pathways." (PMID 40045162, 2025). "Therefore, CNN3 could serve as a potential accurate diagnostic biomarker for patients with osteosarcoma." (PMID 32667904, 2020). "In addition, the abnormal expression profile indicated that CNN3 may promote the clinical progression of osteosarcoma, and the function and underlying mechanism of CNN3 in osteosarcoma were further verified." (PMID 32667904, 2020). "Consequently, CNN3 may serve as a new potential diagnostic tool and therapeutic target for the early detection and treatment of osteosarcoma." (PMID 32667904, 2020). "Correlation between CNN3 protein levels and clinicopathological features of patients with osteosarcoma." (PMID 32667904, 2020). "In this study, we identified high levels of calponin 3 (CNN3) protein in osteosarcoma tissues and cell lines." (PMID 32667904, 2020). "In the future, we will attempt to clarify the regulatory mechanisms involved in the potential oncogenic roles of CNN3 in osteosarcoma." (PMID 32667904, 2020). "We found that CNN3 protein expression was significantly higher in osteosarcoma tissues compared with normal specimens." (PMID 32667904, 2020). "In the present study, we aimed to investigate the role of CNN3 in regulating osteosarcoma progression." (PMID 32667904, 2020). "This was congruent with data showing that CNN3 expression was higher in human osteosarcoma cell lines (MG-63, 143B, and Saos-2) than in the SV40-immortalized normal osteoblastic cell line, hFOB 1.19." (PMID 32667904, 2020). "We determined the potential role of CNN3 as a biomarker for osteosarcoma diagnosis and prognosis and analyzed its function in regulating the proliferation and metastasis of osteosarcoma cell lines in vitro and in vivo." (PMID 32667904, 2020). "CNN3 expression in osteosarcoma cell lines MG-63, 143B, and Saos-2 was higher than that in human osteoblast hFOB 1.19 cells." (PMID 32667904, 2020). "In future studies, we will focus on the regulatory mechanisms of CNN3 by measuring mRNA, non-coding RNA, and protein expression in osteosarcoma cell lines." (PMID 32667904, 2020). "Among the three osteosarcoma cell lines, CNN3 expression was higher in MG-63 and Saos-2, therefore these lines were chosen for subsequent assays." (PMID 32667904, 2020). "Our study provides a potential target for pharmaceutical development and novel therapeutic strategies involving CNN3 inhibition and the control of osteosarcoma growth and metastasis." (PMID 32667904, 2020). "The total score for CNN3 staining in osteosarcoma specimens was significantly higher than that in normal specimens." (PMID 32667904, 2020). "This indicates that U2OS osteosarcoma cells have three copies of CNN3 gene, most likely due to aneuploidy." (PMID 30518778, 2018). "To examine the possible role of Cnn3 in stress fiber assembly in osteosarcoma cells, we generated Cnn3 knockout U2OS cells by CRISPR/Cas9." (PMID 30518778, 2018). "These bioinformatic results are consistent with the results of our in vitro and in vivo experiments, and can further support our conclusion that CNN3 may play an oncogenic role in osteosarcoma progression." (PMID 32667904, 2020).
osteosarcoma (continued). "These demonstrate that CNN3 is highly expressed in osteosarcoma tissues." (PMID 32667904, 2020). "Here, we applied U2OS osteosarcoma cells as a model system to study the function of Cnn3." (PMID 30518778, 2018). "Therefore, we applied 3D structural-illumination microscopy (3D-SIM) imaging to study the localization of Cnn3 in human osteosarcoma (U2OS) cells." (PMID 30518778, 2018). "Therefore, CNN3 may play an oncogenic role during the progression of osteosarcoma by activating the ERK1/2 and p38 pathways." (PMID 32667904, 2020). "Therefore, we hypothesized that CNN3 may be involved in osteosarcoma cell proliferation and metastasis by regulating the MAPK/ERK and p38 MAPK pathways, which play a critical role in osteosarcoma pathogenesis." (PMID 32667904, 2020). "Previous research has shown that knockdown of CNN3 inhibits extracellular signal-regulated kinase 1/2 (ERK1/2) and p38 phosphorylation, reducing osteosarcoma cell activity and proliferation via the mitogen-activated protein kinase (MAPK) signaling pathway." (PMID 39555457, 2024).
breast carcinoma (4 papers, 2017 to 2023). "In this study, we found a significant correlation between CNN3 expression and cancer cell invasiveness in gastric and breast cancer (BC) cells and we demonstrated that CNN3 can positively regulate invasiveness and doxorubicin resistance in GC cells." (PMID 30911294, 2019). "CNN3 (calponin-3) expression is altered in colorectal and breast carcinomas." (PMID 37397367, 2023). "Additionally, upregulation of CA2, CNN3 and AKAP13 was found, which are suggested to be involved in chemotherapy resistance in glioblastoma, colon cancer and breast cancer, respectively." (PMID 33712646, 2021). "We furthermore identified upregulation of the direct EZH2 target genes CNN3 and AKAP13, that are involved in chemotherapy resistance in colon cancer and breast cancer, respectively, and the genes MYO5A, AKT3 and SPECC1, which are implicated in the evasion of apoptosis." (PMID 33712646, 2021). "Western blot data indicated that miR-1 overexpression significantly downregulated WASF2, TWF1, CNN3, TMSB4X and CORO1C, showing that miR-1 could inhibit breast cancer cell metastasis by targeting the WASF2, TWF1, CNN3, TMSB4X and CORO1C genes." (PMID 28159933, 2017).
glioma (3 papers, 2021 to 2024). A benign or malignant brain and spinal cord tumor that arises from glial cells (astrocytes, oligodendrocytes, ependymal cells). "It was also demonstrated that CNN3 was associated with the inflammatory and immune activities of glioma and was involved in checkpoint molecules." (PMID 34797350, 2021). "In the Multivariate Cox regression analysis, histological type (HR = 2.17, 95% Cl 1.71–2.74, P < .001) and CNN3 (HR = 1.00, 95% Cl 1.000–1.003, P = .046) expression in glioma were both independently associated with overall survival." (PMID 34797350, 2021). "These statistical results suggest that CNN3 might serve as a diagnostic biomarker for glioma." (PMID 34797350, 2021). "In the current study, CNN3 was observed to have higher expression levels in glioma samples than normal tissues in the TCGA and GEO datasets." (PMID 34797350, 2021). "Our research aims to explore the prognosis value and immunotherapeutic targetability of CNN3 in glioma patients using bioinformatics approach." (PMID 34797350, 2021). "In the GEO cohort, the expression levels of CNN3 in glioma tissues were significantly higher than it in normal brain tissues (P < .001)." (PMID 34797350, 2021). "CNN3 expression in normal brain and glioma tissues was analyzed according to the RNA sequencing data." (PMID 34797350, 2021). "The results above proposed that CNN3 was putatively related to the immune microenvironment of gliomas." (PMID 34797350, 2021). "The prognosis value of CNN3 in glioma was further investigated by univariate and multivariate analyses." (PMID 34797350, 2021). "Gene expression profiling with clinical information was employed to investigate the correlation between clinicopathological features of glioma patients and relative CNN3 expression levels." (PMID 34797350, 2021). "The predictive value of CNN3 in glioma patients was evaluated by the Kaplan-Meier curve plotted based on the TCGA database." (PMID 34797350, 2021). "High expression levels of CNN3 correlates with a higher degree of malignancy of glioma samples and poorer prognosis." (PMID 34797350, 2021). "CNN3 was enriched in gliomas, and high expression of CNN3 correlated with worse clinicopathological features and prognosis." (PMID 34797350, 2021). "A bioinformatics study has now confirmed CNN3 as a promising immunotherapeutic target in glioma." (PMID 35510040, 2022). "Therefore, our research aims to investigate the prognosis value and immunotherapeutic targetability of CNN3 in glioma patients." (PMID 34797350, 2021). "Moreover, the univariate and multivariate Cox regression analyses further revealed that CNN3 was an independent prognostic biomarker for glioma." (PMID 34797350, 2021). "Herein, we can conclude that CNN3 may be an oncogene for glioma, and high CNN3 expression may contribute to a relatively poor prognosis." (PMID 34797350, 2021). "B7-H3, TIM3, PD-1 and PD-L1 have a significantly positive relationship with CNN3, which indicates that CNN3 might be an immunotherapeutic target in glioma." (PMID 34797350, 2021). "In addition, the Kaplan-Meier analysis illustrated that high CNN3 expression levels predicted worse overall survival in glioma patients." (PMID 34797350, 2021). "CNN3 expression in glioma was analyzed based on GEO and TCGA datasets." (PMID 34797350, 2021). "It revealed that glioma tumors with high CNN3 expression might recruit more immune cells into the tumor microenvironment than gliomas with low CNN3 expression." (PMID 34797350, 2021). "Overall, our study indicated that CNN3 was overexpressed in glioma tissues." (PMID 34797350, 2021). "Finally, further experimental investigations are required to uncover the mechanism of CNN3 overexpression in glioma tissues and explore the relationships among CNN3, immune microenvironment, and glioma progression." (PMID 34797350, 2021). "Therefore, it is proposed that CNN3 may promote gliomas’ progression through its impact on these immunosuppressive cells." (PMID 34797350, 2021).
glioma (continued). "Therefore, CNN3 might be identified as a prognostic molecular marker for glioma according to the results above." (PMID 34797350, 2021). "Moreover, heparan sulfate-glucosamine 3-sulfotransferase 1 (HS3ST1) and calponin 3 (CNN3) are overexpressed in astrocytoma, and mutations in phosphatidylinositol-4,5-bisphosphate 3-kinase catalytic subunit alpha (PIK3CA), PDGFRA, and MYCN are generally associated with poorer prognosis in gliomas." (PMID 39062515, 2024).